RARRES1 (retinoic acid receptor responder 1)
Diseases named in the same sentence as RARRES1 in open-access papers (continued):
Sharing a sentence is not in itself a finding about the gene and the disease.
cancer (25 papers, 2012 to 2026). A tumor composed of atypical neoplastic, often pleomorphic cells that invade other tissues. "Here, we generated Rarres1 knockout (Rarres1-/-) mouse models to study the effects of RARRES1 loss on cancer development, blood cell compartment function, and cellular metabolism." (PMID 35541897, 2022). "Taken together these data demonstrate the association of RARRES1 and fatty acid metabolism in the context of cancer." (PMID 30557378, 2018). "With regard to functional aspects of RARRES1 expression, earlier publications showed that RARRES1 is associated with a regulatory role in cancer invasiveness and tumorigenicity." (PMID 29169400, 2017). "Promoter hypermethylation and loss of RARRES1 seem to facilitate cancer progression." (PMID 36424614, 2022). "Epigenetic silencing of RARRES1 leads to its loss in several types of cancer, including PCa." (PMID 28678839, 2017). "On the other hand, loss of RARRES1 expression in choriocarcinoma cells might be essential for cancer cell invasion into the surrounding tissue." (PMID 29169400, 2017). "We identify RARRES1 as a pivotal regulator of this process, contributing to both therapy resistance and immune exclusion, and propose it as a novel pan-cancer prognostic biomarker." (PMID 41854891, 2026). "The correlation between RARRES1 expression and overall survival was subsequently evaluated in 26 other cancer types based on the TCGA database." (PMID 38533207, 2024). "Previously, retinoic acid receptor responder 1 (RARRES1) was considered a tumor suppressor gene that is downregulated in cancer cells and promotes apoptosis." (PMID 38978060, 2024). "RARRES1, a gene responsive to retinoic acid receptors, displays varied functions in various cancer types." (PMID 38898266, 2024). "In conclusion, RARRES1 is a TNBC-specific predictor whose role is heterogeneous across cancer types." (PMID 38533207, 2024). "We also investigated the predictive value of pre-treatment RARRES1 level for the response to immunotherapy in four published cohorts with other types of cancer." (PMID 38533207, 2024). "In inflammatory breast cancer, RARRES1 mediates the regulatory cancer invasion cells through the Axl pathway." (PMID 36353618, 2022). "In summary, RARRES1 expression is strongly related to cancer progression, survival rate and immune invasion in KIRC patients." (PMID 36353618, 2022). "Cell culture studies in immortalized cell lines showed that Rarres1 depletion augments many cancer phenotypes including: protection from apoptosis and anoikis, anchorage independent growth, and autophagy induction 3,4,8." (PMID 35541897, 2022). "Methylation sequencing revealed that the Rarres1 promoter was commonly methylated in many different cancers and expression of RARRES1 was decreased in a variety of cancers 2,34." (PMID 35541897, 2022). "As our data indicate that RARRES1 has a role in fatty acid metabolism, we wondered if the extensive transcriptomic data available for multiple cancers also points to a relationship with fatty acid metabolism pathways." (PMID 30557378, 2018). "Genes co-expressed with RARRES1 were identified via Oncomine (Compendia Bioscience, Ann Arbor, MI) with respect to each cancer dataset (original data file available upon request)." (PMID 30557378, 2018). "RARRES1 expression was also contextually correlated to fatty acid metabolism genes in multiple cancer types." (PMID 30557378, 2018). "As RARRES1 is highly expressed in differentiated epithelial cells and is silenced in cancer cells, we used selected epithelial cells as our model." (PMID 30557378, 2018). "Instead, RARRES1 depletion renders cancer cells more energetic when starved or treated with C75, mechanisms that trigger fatty acid oxidation, due to the increase in lipid substrates available for fatty acid oxidation." (PMID 30557378, 2018).
cancer (continued). "Of the identified cancers, three (breast, colorectal and prostate) were selected for further analysis given the number of datasets found to have significant RARRES1 gene expression changes." (PMID 30557378, 2018). "The tumor suppressor gene, RARRES1, was reported to be hyper-methylated at its promoter region in several forms of cancer including PCa leading to suppression of RARRES1." (PMID 28678839, 2017). "Since signaling cues in and from cancer cells modulate angiogenesis in vivo, we placed HUVECs in matrigel supplemented with conditioned media (CM) from RARRES1-transfected PCa cells." (PMID 28678839, 2017). "Promoter hypermethylation and loss of the tumor suppressor Retinoic acid receptor responder 1 (RARRES1) were shown to contribute to cancer progression." (PMID 29169400, 2017). "In concurrence with previous reports examining various human cancers, we observed that re-expression of RARRES1 not only augmented cell death induced by cytotoxic agents Paclitaxel and Doxorubicin, but also impeded cell invasion." (PMID 22615834, 2012). "To date, promoter hypermethylation was shown to downregulate RARRES1 expression in a variety of cancers." (PMID 22615834, 2012). "Previously, downregulation of RARRES1 has been confirmed in some human cancers." (PMID 36353618, 2022). "In addition, we found that RARRES1 expression was significantly related to the abundance of 28 types of TILs in heterogeneous human cancers." (PMID 36353618, 2022). "In multivariate analysis, the lack of staining or cytoplasmic staining of RARRES1 was a significant risk factor indicating five times higher risk of cancer relapse." (PMID 32307444, 2020). "Taken together these data indicate that this RARRES1 regulation of mitochondrial function may be particularly important in the action of RA as well as the survival and drug resistance of cancer stem-like populations." (PMID 30899431, 2019). "However the metabolic and phenotypic changes induced by RARRES1 depletion are characteristic of proliferative stem cells and likely activated cancer initiating cells." (PMID 30899431, 2019). "Consistent with this, the RARRES1 gene is heavily methylated in multiple cancers." (PMID 30899431, 2019). "RARRES1 is silenced in cancer cells; therefore normal epithelial cells, where RARRES1 is endogenously expressed, are the best models to use to assess whether PPARs can regulate the expression of RARRES1." (PMID 30557378, 2018). "We used publicly available cancer datasets to assess whether RARRES1 is co-expressed with fatty acid metabolism genes." (PMID 30557378, 2018). "The present study demonstrates an important role for RARRES1 in fatty acid metabolism and may explain the duality of RARRES1 in cancer etiology." (PMID 30557378, 2018). "Cancer cells, in which RARRES1 is silenced, cannot increase RARRES1 protein level after starvation." (PMID 30557378, 2018). "These genes correlate with RARRES1 gene expression changes when all cancers are considered." (PMID 30557378, 2018). "An inhibition of mTOR by RARRES1 expression demonstrate that RARRES1 modulates autophagy and its inhibition in PCa cells may lead to cancer progression." (PMID 28678839, 2017). "Furthermore, loss of both RARRES1 and EB1 protein expression is thought to be associated with the presence of cancer." (PMID 29169400, 2017). "Future studies will help determine the in vivo mechanisms by which RARRES1 may serve as a target for therapeutic intervention both in cancer and in angiogenesis-related disorders." (PMID 28678839, 2017). "RARRES1-triggered enhanced cell-cell contact of cancer cells might mediate contact inhibition of cell proliferation as well as decreased invasiveness and a reduced migratory capability." (PMID 29169400, 2017). "Additionally, expression of the cancer stem cell marker, aldehyde dehydrogenase 1A3, which provides the required ligand (retinoic acid) for RARRES1 transcription, is also specific to the basal-like subtype." (PMID 27286452, 2016).
cancer (continued). "Furthermore, the outcome ascribed to RARRES1 silencing coincided with its clinical applications for treating human cancers." (PMID 22615834, 2012). "RARRES1, a retinoic acid regulated tumor suppressor gene associated with ageing, metabolism and stem cell differentiation is among the most commonly methylated loci in multiple cancers but has no known molecular function." (PMID 30899431, 2019). "However, it was not clear how this activity was linked to the anti-cancer or metabolic effects of RARRES1." (PMID 30899431, 2019). "Although the mechanism of RARRES1 in GBM is still unclear, its mechanism in many other cancers has been studied in depth." (PMID 40002669, 2025). "The distinct function of RARRES1 and its interaction with AGBL2 and other genes in conventional RCC as well as in other types of cancers remains to be cleared." (PMID 32307444, 2020). "Further knowledge of molecular mechanisms of RARRES1 may presumably support the identification of new therapeutic targets for PDAC and other cancers." (PMID 36139565, 2022). "RARRES1 and TNFAIP2 have been commonly investigated in many cancers." (PMID 33587010, 2021). "The exact function of RARRES1 in distinct types of cancers including conventional RCC is not yet determined." (PMID 32307444, 2020). "As depletion of CCP2 or inhibition of VDAC1 reverses the effects of RARRES1 depletion on energy balance and cell survival we conclude that RARRES1 modulation of CCP2-modulated tubulin-mitochondrial VDAC1 interactions is a fundamental regulator of cancer and stem cell metabolism and survival." (PMID 30899431, 2019). "RARRES1, NRIP1, GJB2 and others showed a negative correlation with MAPK12 and might be cancer suppressor genes in DLBCL." (PMID 38773060, 2024). "The expression of RARRES1 in distinct cellular compartment or lack of its expression was significantly correlated with the size, grade, T classification, necrosis and stage of conventional RCC as well as with postoperative cancer relapse (all p < 0.001)." (PMID 32307444, 2020).
infection (2 papers, 2016 to 2021). The state of being infected such as from the introduction of a foreign agent such as serum, vaccine, antigenic substance or organism. "We have not found in the literature any data on the expression of the RARRES1 gene in the chicken cecum and its differential regulation in response to infection with SE, which represents a significant novelty of our results." (PMID 33535430, 2021). "Our data confirm that infection with hrHPV decreases basal STAT1 protein levels in KCs but also show that hrHPV does not interfere with IFNγ-induced STAT1 activation per se, as reflected by STAT1 phosphorylation and increase in RARRES1 and IFITM1 expression." (PMID 27920775, 2016).
metabolic disease (2 papers, 2018 to 2021). A congenital disorder (due to inherited enzyme abnormality) or acquired (due to failure of a metabolically important organ) disorder resulting from an abnormal metabolic process. "RARRES1 is differentially expressed in metabolic diseases and is associated with biological hallmarks that require metabolic reprogramming." (PMID 30557378, 2018). "Our study is the first to demonstrate a direct role for RARRES1 in the changes of lipid metabolism associated with these metabolic diseases." (PMID 30557378, 2018). "Our data is supported by examination of publicly available databases that have listed RARRES1 as one of many genes regulated in metabolic diseases." (PMID 30557378, 2018). "In addition to its role in hepatosteatosis and other metabolic disorders, RARRES1 is among the most commonly methylated genes in multiple human tumors." (PMID 30557378, 2018).
infectious disease (1 paper, 2022). A disorder directly resulting from the presence and activity of a microbial, viral, or parasitic agent in humans. "Modulation of RARRES1 has been identified in response to IFN-γ production in other infectious diseases." (PMID 36504842, 2022).
RARRES1 also shares sentences with these, for which no sentence is quoted: nasopharyngeal carcinoma (4 papers); cervical cancer (3); gastric cancer (2); glioma (2); pancreatic ductal adenocarcinoma (2); psoriasis (2); renal cell carcinoma (2); Skin Cutaneous Melanoma (2); Wilms tumor (2); acne (1); acute myeloid leukemia (1); benign adenoma (1); colorectal adenocarcinoma (1); diffuse large B-cell lymphoma (1); dilated cardiomyopathy (1); focal segmental glomerulosclerosis (1); glaucoma (1); glomerulopathies (1); head and neck squamous cell carcinoma (1); heart disease (1); Hepatic steatosis (1); Hereditary breast cancer (1); IgA nephropathy (1); kidney cancer (1); liver cirrhosis (1); lung carcinoma (1); memory impairment (1); mesothelioma (1); metastatic melanoma (1); nevus (1).
A further 6 diseases each share a sentence with RARRES1 in 1 paper.